CASP8 (caspase 8)
Diseases named in the same sentence as CASP8 in open-access papers (continued):
Sharing a sentence is not in itself a finding about the gene and the disease.
Yersinia infection (31 papers, 2016 to 2026). "Caspase-8 responds to Yersinia infection, an effect that appears to be a combined process of apoptosis, pyroptosis, and necroptosis." (PMID 40191423, 2025). "The IFN-ɣ inducible Z-DNA binding protein, ZBP1, has been shown to play a role in the assembly of the RIPK1-TRIF-caspase-8 complex in response to Yersinia infection." (PMID 39513865, 2024). "It has been suggested that co-assembly of ASC, NLRP3, RIPK3, caspase-1, and caspase-8 triggers PANoptosis during Yersinia infection." (PMID 39058785, 2024). "Yersinia infections in macrophages trigger caspase-8 cleavage of GSDMD, which in turn initiates pyroptosis, and granzyme A, a lymphocyte-derived enzyme, cleaves GSDMB, which in turn triggers pyroptosis in a number of cancer cell types." (PMID 39655049, 2024). "RIPK3 makes no detectable contribution to Yersinia-induced cell death, and we do not observe any evidence for RIPK3-mediated necroptosis during Yersinia infection in the presence of functional caspase-8." (PMID 39058785, 2024). "During Yersinia infection, caspase-8 is activated at endosomal membranes by recruitment to RAGulator complexes." (PMID 39058785, 2024). "In murine BMDMs, TNF or TLR stimulation together with pharmacological TAK1 or IKK blockade induces RIPK1- and caspase-8-dependent cell death, similar to Yersinia infection." (PMID 39186805, 2024). "RIPK3/MLKL-induced programmed necrosis also activates NLRP3, presumably via potassium efflux, thereby providing another route to caspase-1 engagement during Yersinia infection, even when caspase-8 cannot be activated." (PMID 39058785, 2024). "In particular, GSDME was shown to induce Caspase-8-driven pyroptosis in neutrophils, which helps to control systemic Yersinia infections." (PMID 37988464, 2023). "The gasdermin activation via caspase-8 seems to be cell-specific: In response to the Yersinia bacteria infection, caspase-8 directly cleaves GSDMD, whereas GSDME is dispensable for macrophage cell lysis downstream of the ripoptosome." (PMID 37664463, 2023). "In contrast, in Yersinia infection model, like we observed in this study, caspase-8 activates GSDMD to induce cell death." (PMID 36532444, 2022). "In certain settings such as during Yersinia infection of macrophages, CASP8 is able to substitute for pro-pyroptotic CASP1 and CASP11 to cleave GSDMD and execute death." (PMID 33126536, 2020). "Here, we report that caspase-8 plays an essential cell-intrinsic role in innate inflammatory cytokine production in vivo during Yersinia infection." (PMID 27737018, 2016). "Additionally, caspase-3 and caspase-8-dependent pathways can induce pyroptosis: chemotherapeutic agents trigger pyroptosis via caspase-3-mediated cleavage of GSDME, while Yersinia infection induces pyroptosis through caspase-8-mediated cleavage of GSDMD." (PMID 40832104, 2025). "In contrast, caspase-8 promotes TLR4-induced NF-κB activation in mouse B cells independent of its protease enzymatic activity, whereas the production of inflammatory cytokines (TNF, IL-6, IL-12) upon Yersinia infection relies on the protease enzymatic activity of caspase-8." (PMID 38789425, 2024). "Importantly, RIPK1 kinase activity is critical for caspase-8-dependent cell death, restriction of bacterial loads, and host survival during Yersinia infection in mice." (PMID 39186805, 2024). "Whether caspase-8 and caspase-1 are activated downstream of caspase-4 or are acting in a parallel pathway during Yersinia infection of human IECs is unknown." (PMID 37615436, 2023). "Recent studies revealed an alternative pyroptosis pathway executed by GSDMD during pathogenic Yersinia infection driven by a receptor-interacting protein 1 (RIP1)-caspase 8 signaling cascade, which is independent of inflammasomes." (PMID 36248872, 2022).
Yersinia infection (continued). "Interestingly, although some researchers had already identified GSDMD and GSDME activation downstream of caspase-8 after Yersinia infection, in the context of mitochondrial apoptosis, NLRP3 activation induced by K+ efflux seemed to be independent of GSDMD." (PMID 33785842, 2021). "While caspase-8 mediates cell death in response to Yersinia infection as well as other signals, its precise role in gene expression and host defense during in vivo infection is unknown." (PMID 27737018, 2016). "Interestingly, caspase-8 also controls antibacterial immunity and Toll-like receptor-induced cytokine production, and mice lacking caspase-8 are highly susceptible to Yersinia infection." (PMID 30940874, 2019). "In Rip1-/- mice, FLDMs exhibited spontaneous MLKL activation and Yersinia infection led to reduced activation of caspase-1, GSDMD, caspase-3, caspase-7 and caspase-8 compared to wild-type-infected FLDMs." (PMID 39513865, 2024). "Caspase-8, for example, can directly cleave GSDMD in Yersinia infection when transforming growth factor-β-activated kinase 1 (TAK1) is inhibited by YopJ, permitting the activation of caspase-8." (PMID 37895022, 2023). "Caspase-8 can also cleave GSDMD to activate pore formation and cell death during Yersinia infection." (PMID 35563804, 2022). "PANoptosomes have also been identified by immunoprecipitation during Yersinia infection, where RIPK1, RIPK3, caspase-8, FADD, ASC, and NLRP3 can be co-immunoprecipitated." (PMID 35563804, 2022). "Recently, Yersinia infection was found to activate PANoptosis, with infection inducing the formation of a PANoptosome containing RIPK1, RIPK3, caspase-8, ASC, FADD, and NLRP3." (PMID 35563804, 2022). "Consistent with this, caspase-8 is required for optimal production of inflammatory cytokine (TNF, IL-6, IL-12) upon Yersinia infection in both macrophages and in mice." (PMID 33805003, 2021). "Consistent with this, a recent report highlighted that RIPK1-dependent caspase-8 activation leads to GSDMD cleavage and pyroptosis in response to Yersinia infection and that alternative pathways including caspase-11 are recruited when RIPK1 or caspase-8 is impaired." (PMID 41596270, 2026). "In myeloid cells, acetyltransferase Yersinia outer protein J (YopJ) activated GSDME but not GSDMD by promoting RIPK1/caspase-8 pathway to induce myeloid cell pyroptosis and protect host from Yersinia infection." (PMID 38022612, 2023). "In the context of Yersinia infection, RIPK1 is necessary for activation of caspase-1, GSDMD, caspase-8, caspase-3, and caspase-7, but it negatively regulates the activation of MLKL, highlighting the multifaceted modulation of cell death effectors that can occur within PANoptosis." (PMID 35563804, 2022). "The phenomenon that caspase-1 activation requires caspase-8 but is independent of inflammasome components or the adaptor ASC was also reported in Yersinia infection of bone marrow–derived macrophages (BMDMs)." (PMID 34437534, 2021). "In further support of the importance of the TRIFosome in Yersinia infection, cleavage of CASP8 was inhibited nearly entirely in the absence of TRIF, and partially in the absence of ZBP1 and RIPK1 kinase activity in the context of high MOI Yersinia infection." (PMID 33397971, 2021). "Although CASP8 has traditionally been considered as a pivotal apoptotic initiator, accumulating studies have revealed the nonapoptotic roles of CASP8 as initiating cleavage of GSDMD during Yersinia infection." (PMID 32295623, 2020). "Besides caspase-3–dependent pyroptosis, recent study indicated the apoptotic caspase-8 induces cleavage of GSDME and GSDMD to elicit pyroptosis during Yersinia infection, which implied that pyroptosis and apoptosis share many signal transduction pathways." (PMID 30804337, 2019). "Here, we show that caspase-8 activity promotes cell-intrinsic cytokine expression, independent of its role in cell death in response to Yersinia infection." (PMID 27737018, 2016).
Yersinia infection (continued). "Interestingly, upon TLR or death receptor activation, active caspase-8 can cleave the IL-1β precursor into its bioactive fragment at the same site as caspase-1, and can directly cleave GSDMD into its N-terminal fragment, triggering pyroptosis during Yersinia infection." (PMID 36532444, 2022). "Although the NLRP3 inflammasome is activated in response to Yersinia infection or IKK/TAK1 blockade, NLRP3 and the adaptor ASC do not contribute to either caspase-8 or caspase-1 activation or cytotoxicity." (PMID 39058785, 2024). "Nevertheless, our findings provide the first demonstration that enzymatic activity of caspase-8 plays a key cell-intrinsic role in TLR-dependent gene expression and control of Yersinia infection, independent of cell death." (PMID 27737018, 2016). "Despite the lack of a requirement for ASC in caspase-8 or caspase-1 activation or cell death, ASC forms large oligomers in response to YopJ activity, suggesting that ASC complexes play an as-yet-undefined role in Yersinia infection." (PMID 39058785, 2024). "Moreover, neither RIPK3 nor MLKL undergoes phosphorylation in WT cells during Yersinia infection or IKK blockade, suggesting that necroptosis is not activated by Yersinia when caspase-8 is present and functional." (PMID 39058785, 2024).
bladder cancer (27 papers, 2008 to 2025). "Cleaved caspase-8 and -9 and Fas protein expression levels were markedly associated with an increase in the apoptosis of the bladder cancer cells." (PMID 23599794, 2013). "In bladder cancer, promoter methylation of caspase-8 has been identified as a key epigenetic mechanism that reduces its expression, contributing to immune evasion and resistance to cell death, thereby driving tumor progression." (PMID 40555741, 2025). "Activation of both caspase-9 and caspase-8 was observed in the testis tumor cells 48 h after cisplatin treatment, the bladder cancer cell lines responded later and to a lesser extent." (PMID 37891379, 2024). "To clarify the potential molecular mechanism of CASP8 in bladder cancer, we then constructed a regulatory axis of mRNA–miRNA–lncRNA." (PMID 36120583, 2022). "We found that 53.71% of all bladder cancer samples showed genetic mutations in the TCGA bladder cancer cohort and SCAF11 was the most frequent mutation frequency gene, followed by CASP8 and NLRP7." (PMID 36120583, 2022). "As expected, the result of qRT-PCR revealed that CASP8 expression was upregulated in bladder cancer tissue versus bladder tissue (p < 0.001)." (PMID 36120583, 2022). "We also identified an lncRNA SNHG14/miR-20a-5p/CASP8 regulatory axis in bladder cancer by constructing a ceRNA network." (PMID 36120583, 2022). "Further vivo and vitro experiments are necessary to verify the lncRNA SNHG14/miR-20a-5p/CASP8 regulatory axis in bladder cancer." (PMID 36120583, 2022). "Collectively, these data suggest the involvement of a caspase-8–mediated extrinsic signaling pathway followed by downstream activation of caspase-3 in the apoptosis elicited by overexpression of AT2R in bladder cancer cells." (PMID 28599664, 2017). "Evodiamine activated caspase-9 and caspase-8 in bladder cancer cells 253J and T24, indicating that both the intrinsic and extrinsic apoptotic pathways were involved in the evodiamine-induced apoptosis." (PMID 24566141, 2014). "Further studies are needed to investigate the relationship between caspase-8 activation and the intrinsic mitochondrial pathway in evodiamine-treated bladder cancer cells." (PMID 24566141, 2014). "Compared with the vector control, the expression of active (cleaved) caspase-8 in the two bladder cancer cells was significantly increased treated with LRIG1 gene." (PMID 24314030, 2013). "Cleaved caspase 8 suggests an autocrine signal(s) following dnStat3 transduction in bladder cancer cells." (PMID 18939995, 2008). "Furthermore, the univariate and multivariate analyses suggested that CASP8 expression and clinical stage as independent factors affected the overall survival of bladder cancer patients." (PMID 36120583, 2022). "All these pieces of evidence revealed that the lncRNA SNHG14/miR-20a-5p/CASP8 regulatory axis may also play vital functions in the progression of bladder cancer." (PMID 36120583, 2022). "Moreover, the Kaplan–Meier curve revealed that bladder cancer patients with high CASP8 expression had a poor overall survival (p = 0.0016)." (PMID 36120583, 2022). "Moreover, this combination strongly increased the levels of cleaved caspase-8 and cleaved caspase-3 in all three bladder cancer cells." (PMID 35985770, 2022). "By constructing an mRNA–miRNA–lncRNA network, we identified an lncRNA SNHG14/miR-20a-5p/CASP8 regulatory axis, which may play a vital role in the development of bladder cancer." (PMID 36120583, 2022). "PES also induces caspase-8-dependent death receptor-mediated apoptotic pathways in bladder cancers." (PMID 32110810, 2020). "Moreover, higher dosages of CuE (0.5–1 μM) induced the up-regulation of Fas/CD95, truncated BID (t-BID), AIF, and sequential activation of caspase-8, caspase-9, and caspase-3 in T24 bladder cancer cells." (PMID 25072848, 2014).
bladder cancer (continued). "Similarly, cleavages of caspase-3 and PARP proteinswere also observed in the same patterns as caspase-8, suggesting extrinsicapoptotic pathway was selectively activated in bladder cancer cells whenAd5-TRAIL-MRE-1-133-218 was used." (PMID 23442927, 2013). "Therefore, the lncRNA SNHG14/miR-20a-5p/CASP8 regulatory axis may play a vital role in the progression of bladder cancer." (PMID 36120583, 2022). "To control the specificity of CD40-mediated and caspase-8–dependent cell death in an in vitro assay with CD8+ T cells, human EJ138 bladder carcinoma cells, and A704 renal adenocarcinoma cells, we generated CD40−/− and caspase-8−/− variants of both lines." (PMID 40397730, 2025). "As caspase-8, which is downstream in the death receptor pathway, is activated upon cisplatin treatment, it was, therefore, investigated whether factors involved in death receptor signaling were regulated in a different way in testicular and bladder cancer cell lines after cisplatin treatment." (PMID 37891379, 2024). "Similar results were seen in bladder cancer cells: PA-MSHA induced time- and concentration-dependent inhibition of tumor cell growth by stimulating protein expression of cleaved caspase-8 and -9, as well as Fas protein." (PMID 38339275, 2024). "In the T24 bladder cancer cell line, THP treatment significantly increased the expression of apoptosis-related proteins, such as BAX, cleaved caspase-3, caspase-8, and caspase-9, while the expression level of anti-apoptotic protein BCL-2 was inhibited." (PMID 37173953, 2023). "By comprehensive analysis of the prognostic value and immune infiltrates of PRGs in bladder cancer, we identified a pyroptosis-related prognostic signature and the lncRNA SNHG14/miR-20a-5p/CASP8 regulatory axis for bladder cancer." (PMID 36120583, 2022). "The Univariate Cox regression analysis revealed that eight PRGs (PRKACA, GSDMB, CASP9, GSDMD, CASP6, CASP8, AIM2, and CASP1) were significantly correlated with the prognosis in bladder cancer." (PMID 36120583, 2022). "Western blot analysis demonstrates that BIX-01294 (0, 5, 10 μmol/l) significantly activated CASP8, CASP9, CASP3 and cleaved the substrate of CASP3, PARP1 in bladder cancer cells treated for 24 hours." (PMID 25685062, 2015). "The data showed that caspase-8 wascleaved in Ad-TRAIL and Ad-TRAIL-MRE-1-133-218-infected bladder cancer cells aswell as Ad-TRAIL-infected BMCs." (PMID 23442927, 2013). "For example, in the bladder cancer cell line T24, CuE administered at 0.5–1 μM induced apoptosis and triggered up-regulation of Fas/CD95, truncated BID (t-BID), apoptosis-inducing factor (AIF), and sequential activation of caspase-8, caspase-9, and caspase-3." (PMID 25072848, 2014). "Moreover, inhibitors of either caspase-3/7 (z-IEVD-fmk) or caspase-8 (z-IETD-fmk) significantly reduced the impact of TYRO3 depletion on cell survival, demonstrating the crucial importance of apoptosis regulation for TYRO3 activity in bladder cancer cells." (PMID 30765874, 2019).
multiple myeloma (25 papers, 2008 to 2025). "Bortezomib requires caspase-8 and caspase-9, whereas marizomib induces the apoptotic effect mainly through caspase-8 signaling that allows it to overcome the resistance of myeloma cells conferred by Bcl-2 mutations." (PMID 26579531, 2015). "It was previously shown that MCP induces apoptosis in multiple myeloma cells and triggers apoptosis associated with activation of caspase-8 and caspase-3 pathway followed by proteolytic cleavage of poly (ADP-ribose) polymerase PARP." (PMID 27551476, 2015). "However, the overactivation of caspase-8 has been found in drug-resistant myeloma cells and, in some cancers, caspases such as caspase-8 and caspase-9 are linked to increased tumorigenesis, survival and invasion." (PMID 37686623, 2023). "Next, we would like to test whether the gene expression of CASP-8 is associated with the clinical outcome of myeloma patients." (PMID 33392195, 2020). "Myeloma cell death was associated with dual PI and Annexin-V positivity and increased expression of apoptotic genes, including CASP1, CASP8, CASP9, BAX, BID, and FASL." (PMID 36992311, 2023). "Oppositely, THD up-regulates the caspase-8 protein widely used in myeloma by inducing caspase-8 myeloma cell programmed cell death apoptosis." (PMID 37110201, 2023). "GCS-100 also reduced bortezomib resistance and increased dexamethasone-induced apoptosis in multiple myeloma cells via caspase 8 (CASP8)/CASP3 PARP pathway activation." (PMID 36364232, 2022). "In this minireview, the caspase-8-involved extrinsic cell death cascade in bortezomib and lenalidomide therapy for myeloma was evaluated." (PMID 35321428, 2022). "In this mini-review, I summarized recent advances in determining the molecular mechanisms of caspase-8 in bortezomib–lenalidomide-based therapy for myeloma and explored the possible functions of caspase-8 in the proliferation and apoptosis of myeloma cells." (PMID 35321428, 2022). "Second, I summarize the recent advances in bortezomib and lenalidomide treatment in multiple myeloma and survey the different biological roles of caspase-8 in the treatment of myeloma." (PMID 35321428, 2022). "Caspase-8, as an initiator caspase, is essential for death receptor-dependent apoptosis and is activated in multiple pharmacological treatments for myeloma." (PMID 35321428, 2022). "Given that myeloma is a cancer of plasma cells, which are differentiated lymphocytes, the possible functions of caspase-8 in the proliferation of myeloma cells need to be further investigated." (PMID 35321428, 2022). "Taken together, our results demonstrated that both inhibition and knockdown of CASP-8 enhance the anti-myeloma activity of Len in cell lines." (PMID 33392195, 2020). "This indicates that CRBN is required for the enhanced anti-myeloma activity of Len upon CASP-8 inhibition." (PMID 33392195, 2020). "Bor is a widely used proteasome inhibitor known to induce apoptosis through caspase-8 and caspase-9 signaling which further leads to caspase-3 activation in multiple myeloma cells." (PMID 32653014, 2020). "Database analysis showed that CASP-8 mRNA expression is inversely correlated with the overall survival rate of myeloma patients." (PMID 33392195, 2020). "On the one hand, we discovered that the viability of myeloma cells is reduced by the addition of CASP-8 inhibitor during the Len treatment." (PMID 33392195, 2020). "To further determine the role of CASP-8 on the anti-myeloma activity of Len, we established MM1.S and CAG cell lines stably expressing control shLacZ or shCASP-8." (PMID 33392195, 2020). "Angular pyranocoumarin extracted from P. praeruptoruom reportedly inhibits proliferation and induces apoptosis in human U266 myeloma cells by upregulating caspase-8 and caspase-3 proteins and downregulating phospho-ERK and phospho-AKT proteins and hTERT mRNA." (PMID 32244796, 2020).